SPTLC3 (serine palmitoyltransferase long chain base subunit 3)
Description:
Component of the serine palmitoyltransferase multisubunit enzyme (SPT) that catalyzes the initial and rate-limiting step in sphingolipid biosynthesis by condensing L-serine and activated acyl-CoA (most commonly palmitoyl-CoA) to form long-chain bases. The SPT complex is composed of SPTLC1, SPTLC2 or SPTLC3 and SPTSSA or SPTSSB. Within this complex, the heterodimer consisting of SPTLC1 and SPTLC2/SPTLC3 forms the catalytic core. The composition of the serine palmitoyltransferase (SPT) complex determines the substrate preference. The SPTLC1-SPTLC2-SPTSSA complex shows a strong preference for C16-CoA substrate, while the SPTLC1-SPTLC3-SPTSSA isozyme uses both C14-CoA and C16-CoA as substrates, with a slight preference for C14-CoA. The SPTLC1-SPTLC2-SPTSSB complex shows a strong preference for C18-CoA substrate, while the SPTLC1-SPTLC3-SPTSSB isozyme displays an ability to use a broader range of acyl-CoAs, without apparent preference.
Synonyms: LCB2b; LCB 3; SPT 3; C20orf38; SPTLC2L; FLJ11112; hLCB2b; LCB3; SPT3; dJ718P11; dJ718P11.1
Tractability: Antibody: UniProt predicts a signal peptide or a membrane-spanning region. PROTAC: ubiquitination databases record sites on it; its protein half-life has been measured.
Target class: Enzyme; Transferase
Gene: Protein-coding gene on chromosome 20 (13,008,972 to 13,169,103, forward strand). Ensembl gene ENSG00000172296.
Subcellular location: Endoplasmic reticulum membrane
Subcellular location (Human Protein Atlas): Microtubules
Pathways (Reactome):
Metabolism: Sphingolipid de novo biosynthesis
Gene Ontology:
Molecular function: protein binding; serine C-palmitoyltransferase activity; pyridoxal phosphate binding; transferase activity
Biological process: sphingoid biosynthetic process; sphingosine biosynthetic process; ceramide biosynthetic process; sphingolipid biosynthetic process; sphingolipid metabolic process
Cellular component: serine palmitoyltransferase complex; endoplasmic reticulum membrane
Genetic constraint (gnomAD): Loss-of-function variants: 37 observed, 56.56 expected, observed/expected ratio (o/e) 0.65, 90% interval 0.5 to 0.86. The upper end of that interval is the gene's LOEUF score, 0.86, which puts it in group 3 of 6, group 1 being the genes least tolerant of losing a copy. Missense variants: 552 observed, 623.75 expected, observed/expected ratio (o/e) 0.88, 90% interval 0.82 to 0.95. Synonymous variants: 219 observed, 220.72 expected, observed/expected ratio (o/e) 0.99, 90% interval 0.89 to 1.11.
Homologues: Orthologues: chimpanzee SPTLC3 (99% identical), macaque SPTLC3 (97% identical), dog SPTLC3 (90% identical), rabbit SPTLC3 (88% identical), pig SPTLC3 (87% identical), tropical clawed frog sptlc3 (74% identical), rat Sptlc3 (71% identical), mouse Sptlc3 (70% identical), zebrafish sptlc3 (69% identical). Paralogues in human: SPTLC2 (70% identical), ALAS2 (23% identical), SPTLC1 (23% identical), ALAS1 (23% identical), GCAT (21% identical).
Diseases named in the same sentence as SPTLC3 in open-access papers:
SPTLC3 is named in the same sentence as 34 diseases in open-access papers, as found by Europe PMC text mining. Sharing a sentence is not in itself a finding about the gene and the disease. The quoted sentences say what the papers report.
diabetes (3 papers, 2017 to 2021). "Sptlc3 and Enpp7 exhibited the largest transcriptional changes associated with the progression of untreated diabetes suggesting that changes in ceramide/sphingolipid metabolism to support the enlargement of the mucosal luminal interface." (PMID 34806320, 2021). "A number of CER[NS] species have been studied as potential biomarkers of CVD and diabetes, and data from others have suggested that the SPTLC3 locus is associated with these CERs." (PMID 33437986, 2021). "Overall, Sptlc3 and Enpp7 had the largest transcriptional changes and seem to support a proliferative effect of the mucosa during the advancement of diabetes." (PMID 34806320, 2021).
hepatocellular carcinoma (2 papers, 2015 to 2023). A malignant tumor that arises from hepatocytes. "However, expression of SPTLC3 subunit is barely detectable in normal liver, although its levels increase in hepatocellular carcinoma." (PMID 26539645, 2015).
Insulin resistance (2 papers, 2019 to 2024). Increased resistance towards insulin, that is, diminished effectiveness of insulin in reducing blood glucose levels. "Moreover, chronic SFA treatment of diet-induced obese mice alleviated insulin resistance and decreased ceramide contents by regulating the expression of ceramide biosynthesis-related gene SPTLC3." (PMID 31137828, 2019). "Collectively, our study revealed a new mechanism underlying SFA’s insulin-sensitizing properties and suggested that therapeutically targeting ceramide synthesis through inhibiting SPTLC3 might be an effective therapeutic for insulin resistance." (PMID 31137828, 2019). "In addition, knockdown of serine palmitoyltransferase 3 (SPTLC3) in HepG2 cells prevented ceramide accumulation and alleviated insulin resistance." (PMID 31137828, 2019). "We conclude that SFA recovers glucose homeostasis and improves insulin sensitivity by blocking ceramide biosynthesis through modulating SPTLC3, indicating that SFA may be a potential candidate for prevention and amelioration of hepatic insulin resistance via a ceramide-dependent mechanism." (PMID 31137828, 2019).
myocardial infarction (2 papers, 2017 to 2023). Gross necrosis of the myocardium, as a result of interruption of the blood supply to the area, as in coronary thrombosis. "In other cardiovascular disease models, a genome-wide association study (GWAS) has reported SPTLC3 genetic variants to be associated with protective odds for myocardial infarction." (PMID 38087395, 2023). "Another study demonstrated that the SNP of rs3848751 in SPTLC3 was associated with HDL-C and LDL-C in males and variants (rs3848751 and rs6078888) within SPTLC3 had influence on the risk of myocardial infarction." (PMID 28056980, 2017).
angina (1 paper, 2019). "These included novel associations of variants at COL5A1 with cerebrovascular disease (P = 4.6 × 10−4), GALNT16 with angina (P = 9.3 × 10−4), MBOAT7 with venous thromboembolism (P = 1.3 × 10−3), GLTPD2 with atherosclerosis (P = 5.3 × 10−4) and SPTLC3 with intracerebral haemorrhage (P = 1.0 × 10−3)." (PMID 31551469, 2019).
cholesteatoma (1 paper, 2022). A pathologic process characterized by the proliferation of keratinizing squamous epithelium resulting in the accumulation of keratin and cells in the middle ear and/or mastoid. "However, in our own middle ear expression dataset from the same patients, all 12 genes were DEGs for cholesteatoma: RTN4, RAB5A, CRYBG1, RGS22, HEPHL1, and SPTLC3 were upregulated, while APBB1IP, BHLHE41, ARID3A, C5AR1, CPT1B, and FAM227A were downregulated." (PMID 36699445, 2022).
dementia (1 paper, 2023). Loss of intellectual abilities interfering with an individual's social and occupational functions. "Since associations between cardiovascular events and dementia have often been cited, it is plausible that SPTLC3 or other SP synthesis-associated enzymes may be playing important roles in pathophysiology of dementia." (PMID 38087395, 2023).
Hepatic steatosis (1 paper, 2023). Steatosis is a term used to denote lipid accumulation within hepatocytes. "N-3 PUFAs downregulate Sptlc3 and Degs2-CerS corresponding genes, reducing CerS activity (Cer16:0, Cer18:0, Cer20:0, Cer22:0, and Cer24:0) and decreasing hepatic steatosis in a hyperhomocysteinemia-induced hepatic steatosis mouse model." (PMID 36904216, 2023).
intracerebral haemorrhage (1 paper, 2019). "We found that the CER (d18:1/24:1) decreasing variant SPTLC3 rs364585-G was associated with decreased risk of intracerebral haemorrhage, while CER (d18:1/24:0) increasing variant ZNF385D rs13070110-C was nominally associated with increased risk of intracerebral haemorrhage." (PMID 31551469, 2019). "We identified two variants near SPTLC3 and ZNF385D that modulate the plasma levels of CER (d18:1/24:1) and CER (d18:1/24:0), respectively, and risk for intracerebral haemorrhage." (PMID 31551469, 2019).
lactose intolerance (1 paper, 2018). "We evaluated associations of C17:0 and C15:0 with SNPs in the LCT, and C23:0 with SNPs in CERS4, and SPTLC3 genes, providing new insights on potential influence of adult-onset lactose intolerance and sphingolipid synthesis on circulating levels of C17:0 and C23:0 respectively." (PMID 29738550, 2018).
neuropathy (1 paper, 2024). A disorder affecting the nervous system that manifests with pain, tingling, numbness, and/or muscle weakness. "SPTLC3 is only conserved in Euteleostomi, and it has been reported playing an important role in cardiovascular diseases and neuropathy." (PMID 39698091, 2024).
Obesity (1 paper, 2015). Accumulation of substantial excess body fat. "In the obesity study, strong genetic control of body fat set-point as well as microbiome plasticity was unraveled, and multiple genetic loci were identified for obesity traits and dietary responses (e.g., Sptlc3, Klf14, Degs1, Npc, Cbr1, and amylases)." (PMID 26202330, 2015).
psoriasis (1 paper, 2022). An autoimmune condition characterized by red, well-delineated plaques with silvery scales that are usually on the extensor surfaces and scalp. "For example, in psoriasis lesional skin, SPTLC2 was upregulated and SPTLC3 was downregulated, which would increase the synthesis of ceramides with 18-carbon sphingoid bases and decrease the synthesis of ceramides with long-chain sphingoid bases." (PMID 35900871, 2022).
Sepsis (1 paper, 2023). Sepsis is defined as life-threatening organ dysfunction caused by a dysregulated host response to infection. "Additionally, they found that serine palmitoyltransferase 3(SPTLC3) was negatively correlated with patterns of disease progression in sepsis." (PMID 38343439, 2023).
cancer (1 paper, 2021). A tumor composed of atypical neoplastic, often pleomorphic cells that invade other tissues. "The skin/cancer-related genes in the most significant focally amplified regions worth mentioning are STIM2 (chr4p15.2; q=0.16; occurring in 2 samples), KLRB1/CD161 (chr12p13.31; q=0.007; occurring in 2 samples), and SPTLC3 (chr20p12.1 q=0.23; occurring in 2 samples)." (PMID 34900699, 2021).
tumor (1 paper, 2023). "The expression level of SPHK1 (p = 0.007) was significantly positively correlated with the tumor proliferation signature instead of SPTLC3 (p = 0.616) using ssGSEA analysis." (PMID 37999228, 2023).
SPTLC3 also shares sentences with these, for which no sentence is quoted: cardiovascular disease (3 papers); atherosclerosis (1); Brain atrophy (1); cerebrovascular disease (1); Cognitive impairment (1); coronary artery disease (1); gastric cancer (1); glioblastoma (1); gout (1); liver cancer (1); melanoma (1); otitis media (1); prostate carcinoma (1); renal cell carcinoma (1); type 2 diabetes (1); venous thromboembolism (1); Wilms tumor (1); Wilson disease (1).